IFNG (interferon gamma)
Diseases named in the same sentence as IFNG in open-access papers (continued):
Sharing a sentence is not in itself a finding about the gene and the disease.
infection (continued). "However, there was approximately two folds increase in mRNA expression of IFNγ and TNF-α in BA.5 infection when compared to its parental B.1.1.529 infection." (PMID 37704701, 2023). "The MHV-JHM v2.2-1 infection of CCR2−/− mice was much more severe, resulting in a lack of virus control due to limited myeloid and T cell CNS infiltration accompanied by impaired Ifnγ and Ccl5 expression." (PMID 38140641, 2023). "However, after infection with the H7N7, vaccination resulted in significantly lower CCL2 (p = 0.003) and IFNγ (p = 0.01) levels in the lungs of young mice compared with unvaccinated infected mice." (PMID 37063291, 2023). "With the use of interferon gamma release assays, studies have demonstrated that the BCG vaccine not only prevents acquisition of an M. tb infection, but it also prevents progression of the infection to active disease." (PMID 36835324, 2023). "The inhibitory effect of infection on IFNγ appears to be general, antigen- and adjuvant-non-specific, because it was also observed after polyclonal T cell stimulation and independent of the pattern recognition receptor pathway triggered by the adjuvant used." (PMID 36753434, 2023). "Notable among these cytokines are TNFα, IL-1β, and IFNγ, where differences in IL-1β and IFNγ secretion between AUD and non-AUD cells were significant and there was a trending higher level of TNFα secretion by AUD cells at 6 and 24 h after infection." (PMID 37786945, 2023). "moshkovskii infection had significantly lower mean IFNγ concentrations (p = 0.039) compared to those with no infection." (PMID 37111135, 2023). "However, in 2001, an interferon gamma release assay (IGRA) was developed which can detect TB and discriminate infection from inoculation with the BCG vaccine and other mycobacterial infections." (PMID 36835324, 2023). "When we gavaged naïve recipient mice with 1/6th of the brains from the infected mice, TgVEG:WT brain homogenates induced detectable serum IFNγ by D6 post-infection while we detected no IFNγ in mice orally infected with mutant parasite brain homogenates." (PMID 37770433, 2023). "OT-I CD8+ T cells were recruited equally to both the control (N4-infected) and experimental (APL-infected) skin on day 7 post infection, but the frequency of OT-I CD8+ T cells expressing IFNγ directly correlated with the strength of TCR signal received within the VacV-infected skin microenvironment." (PMID 37402742, 2023). "We observed IFNγ-producing CD8+ T cells also in type-2 and type-3 infections." (PMID 37696824, 2023). "Intriguingly, the effect of itaconic acid pre-stimulus on macrophages, in the absence of infection or IFNG activation, was upregulation of Icosl and downregulation of Cd86, with statistically significant differences compared to the control." (PMID 37235312, 2023). "We further identified the minimal CD8+ T-cell epitopes in the viral Gc proteins and that infection of mice lacking IFNγ resulted in worsened disease and higher viral loads." (PMID 37866114, 2023). "The mechanisms by which the Sts proteins regulate IFNγ signaling in the context of a F. tularensis LVS infection are not known." (PMID 37240179, 2023). "IAV-specific CD4 T cells in the lung did not display increased expression of CD69, ICOS, or Ifnγ following re-infection." (PMID 37842651, 2023). "In our study, all patients had a tuberculin skin test or interferon-gamma release assay along with a chest radiograph within 90 days prior to enrollment, and patients in whom there as concern for infection were not enrolled." (PMID 37294447, 2023). "However, IFNγ-secreting SARS-CoV-2 T cells against M and N proteins in the lung were better preserved from the original infection one year later than were responses against the S protein enhanced due to vaccination." (PMID 37019909, 2023). "We observed no reduction in MHC-II, CD80/86 and CD40 expression after infection, and similar levels of IFNγ production by Th1 cells were observed in time course studies." (PMID 38114497, 2023).
infection (continued). "We found that the levels of TNFα, IL-6, and IFNγ were comparable in control and butyrate-treated mice 18 hours post-infection, suggesting that butyrate did not dampen pro-inflammatory cytokine production in the airways during infection." (PMID 37178819, 2023). "IFNγ priming reduced the intracellular Mtb growth by 3–4 fold in wild type macrophages, but not IFNγR−/− BMDMs at 5 days post infection (dpi)." (PMID 36769182, 2023). "When analyzing pro-inflammatory cytokine gene expression, we observed a significant increase in gene expression at d7 p.i. of IL-1β and IFNγ with no change of TNF or iNOS expression in p.o. infected mice when compared to i.p. infection." (PMID 35898505, 2022). "We first infected IFNG- and IFNGR1-knockout cell lines with HSV-1, a double-stranded DNA virus that can be propagated in the Vero cell line, at a multiplicity of infection (MOI) of 0.1 for 72 h and then observed the cytopathic effects daily under a light microscope." (PMID 35897807, 2022). "We observed that there was a significantly higher level of IL-12 and IFNγ at 7 d.p.i. upon i.p. infection and nominally, but non-significantly, higher expression of TNF and IL-1β." (PMID 35898505, 2022). "This suggests that GM results in increased responsiveness before and during the start of SE infection by stimulation of degranulation rather than IFNγ production as effector pathways of these cells." (PMID 35120583, 2022). "We, therefore, quantified SC mRNA levels encoding various pro-inflammatory and disease resolving factors, namely, the monocyte chemoattractant CCL2, TNF, IFNγ, a prominent mediator of MHV virus control, iNOS, IL10 and arginase 1 (Arg1) over the course of infection." (PMID 36333761, 2022). "Indirect immunofluorescence co-labelling of MCM2 and the LT-Ag revealed that infection with BKPyV triggered a significant increase in the proportion of MCM2 positive cells and that significantly fewer cells became MCM2 positive in the presence of IFNγ." (PMID 35194151, 2022). "We explored the relevance of our findings in the context of ONNV human infection by treating four human cell lines from different nonimmune lineages (fibroblast, synoviocyte, endothelial, and skeletal muscle cells) with IFNγ before ONNV infection." (PMID 35039441, 2022). "None of the cytokines (IL-1β, TNF and IFNγ) were able to prevent the reduction in TEER upon infection with B. pertussis (data not shown)." (PMID 35256671, 2022). "Other pro-inflammatory cytokines such as IL-6 and IFNγ did not present a significant increase over the first two weeks of infection." (PMID 35313622, 2022). "In vitro, pretreatment with IFNγ of CT (svD) infected epithelial cell induces the depletion of the tryptophan pool, leading to no infection of the cells." (PMID 36560972, 2022). "This is, in itself, still debatable because numbers of IFNγ-producing cells or IFNγ levels did not correlate with survival of challenge infections in several studies." (PMID 35215216, 2022). "Infection also elicited production of the type 1 cytokine, IFNγ, in the peritoneum of SPF but not antibiotic-treated mice." (PMID 35288644, 2022). "Indeed, early studies have suggested that Xcl1 functions in concert with IFNγ, MIP1α, MIP1β, and RANTES in promoting Th1 responses after infection." (PMID 35296089, 2022). "We found cytokines like IFNγ, IL-4, IL-13, IFNβ1, TNFα, and transcriptional regulators such as HIF1α, STAT1, CTCF, TP73, IRF1, MXD1, ATF4, SPI1 mediate macrophage activation upon infection." (PMID 35789215, 2022). "NK cells eliminate target cells through direct cell-to-cell contact-based NK cell cytotoxicity (NKCC) and by secreting cytokines, such as interferon gamma (INF-γ) or tumor necrosis factor alpha (TNF-α), which recruit additional immune cells to the site of infection or inflammation." (PMID 35326467, 2022).
infection (continued). "As the infection progresses to d28 p.i., there is comparable total numbers of IFNγ+ CD4 and CD8 T cells between infection routes, whereas both CD4+IFNγ+ and CD8+IFNγ+ cells are producing significantly higher amounts of IFNγ upon i.p. infection compared to p.o.." (PMID 35898505, 2022). "For example, while IFNγ-producing T cells are critical for protective immunity in standard inbred lines of mice, a significant fraction of humans exposed to Mtb control the infection without producing a durable IFNγ response." (PMID 35112666, 2022). "Interestingly, IFNG was strongly expressed in VAT in the SIV+ART+ group, as were TNFA and CXCL10—suggesting that the duration of infection and/or ART significantly impacted the type II IFN pathway as well." (PMID 36231066, 2022). "On day 7 post-infection period, cytokine gene expression levels showed overall no different expression among the mice group, except for IFNG." (PMID 36006302, 2022). "Over the course of infection, no significant changes were observed in memory T cell populations or intensity of IFNγ or CD62L expression among placebo challenged animals as compared to status of these animals at 0 dpc." (PMID 36558773, 2022). "Infection with Omicron or Delta led to a rapid and similar increase in antibodies to the receptor-binding domain (RBD) of Omicron protein and spike peptide-induced interferon gamma in whole blood." (PMID 36159859, 2022). "GM supplementation enhanced expression of CD107 on intraepithelial NK cells but not IFNγ expression before infection, and a similar trend was observed for intraepithelial CD8+ T cells." (PMID 35120583, 2022). "We recently observed that infection with either attenuated (NH/P68) or virulent (22653/14) ASFV resulted in moMφ impaired ability to release IL-12, IL-6, and TNF-α in response to stimulation with IFNγ and LPS or a TLR2 agonist." (PMID 35215216, 2022). "Consequently, we observed enhanced IFNγ+ LCMV NP396-specific CD8+ T cells after αPD-L1 therapy compared to untreated mice, as well as increased clearance of the chronic LCMVcl13 infection, which is in line with previously published data." (PMID 36298848, 2022). "Consequently, interferon gamma (IFN-γ) and tumor necrosis factor alpha (TNF-α) are critical in fighting infections, and ultimately for cell survival mechanisms." (PMID 35962424, 2022). "In contrast, IL-22 injection into Il-18−/− mice failed to promote mucin secretion, which is reminiscent of the results that IL-22 injection also failed to restore Paneth cell or IFNγ response in Il-18−/− mice during AIEC infection." (PMID 35169117, 2022). "IFNγ exposure reduced mean MCM2 and MKI67 transcript expression in BKPyV-infected cultures compared with infection alone but, due to the variance in the IFNγ-response, these changes were not statistically significant." (PMID 35194151, 2022). "Here we use mice lacking IFNγ as they exhibit 100-fold higher infections than that observed in wild type, providing a greater dynamic range to study the utility of exogenous IFNλ treatment." (PMID 35584177, 2022). "Importantly, lung gene transcript expression was consistent with the cellular phenotype and functional data, with T cell responses including TBET, IFNG, GZMB, and PRF1 upregulation throughout infection." (PMID 36146518, 2022). "We found a reduction in the percentage of viable (Annexin V- PI-) thymocytes after infection, independent of IFNγ and iNOS." (PMID 34987496, 2021). "However, what was striking was the lower abundancy of proteins involved in response to infection (ISG15, NME2, IFNγ, and C3)." (PMID 34962717, 2021). "Importantly, upregulation of IFNG plays a pivotal role in combating both CVS and Nigerian street rabies virus (SRV) strains at early phases of infection." (PMID 34769416, 2021).
infection (continued). "The T helper 1 cells release cytokines (interferon gamma [IFN-γ] and tumor necrosis factor alpha [TNF-α]) at the site of infection and activate macrophages and DCs to produce cytokines and antimicrobial peptides for containment of the infection." (PMID 33087432, 2021). "This is consistent with original in vitro studies which revealed no antiviral effect of IFNγ and even enhancement of infection in primary cells and several clinical trials that revealed no impact of this cytokine in vivo." (PMID 34951583, 2021). "Although the mRNA levels of IFNγ increased exceedingly upon infection, it was not modified by At-RvD1 or Bz in WT and FPR2-/- mice." (PMID 34784372, 2021). "Together, these results show that the increase on LSK cells percentage during infection by M. avium strain 25291 is partially dependent on IFNγ-induced activation of Mφ but not on iNOS production." (PMID 34987496, 2021). "The “tuberculin skin test (TST)” and “interferon-gamma release assays (IGRA)” are used globally to determine exposure to Mtb but are not ideal for predicting recent infection or active Tb disease, especially in high TB endemic areas." (PMID 34631731, 2021). "While responses were comparable at baseline, Tanzanians showed lower lymphocyte IFNγ production after CHMI and the immunosuppression, still recognizable 1 month later, was suspected to be produced by the blood stage exposure during CHMI infections." (PMID 34684226, 2021). "There have been no previous reports as to the role of IDO1 during infection in A549s and as such we generated an IDO1 deficient A549 cell line and challenged with CTG-GFP in the presence of IFNγ." (PMID 34871166, 2021). "Significantly higher amounts of IFNγ, IL-4, and GM-CSF were observed in the rAd5-YFV trivalent vaccine-immunized mice when compared to animals vaccinated with the rAd5-LcrV monovalent vaccine in response to infection." (PMID 33514747, 2021). "Moreover, spheroid infection with such an SFV/IFNg virus dose provided up to 15 ng/mL of vdIFNg production, as confirmed by quantitative anti-IFNg ELISA, which is a sufficient amount for macrophage activation." (PMID 34835178, 2021). "Levels of IFNγ+ T-cells were remarkably low three months after infection, and declined marginally in a non-significant manner between three and twelve months post-infection." (PMID 34960185, 2021). "Cumulatively, further studies are needed to precisely define why mice with absent T-cells or IFNγ signaling succumb to the infection." (PMID 33572859, 2021). "To address the possible effects of IFNγ on inflammatory signalling in vivo, we micro-dissected out the infection sites from animals with and without splenectomies and performed Luminex screening." (PMID 34015044, 2021). "Irrespective of serotypes, IFNγ was significantly elevated in all serotypes than control as well as in primary infection than secondary, indicating its role in immune response." (PMID 34447698, 2021). "To investigate the immediate effect of the presence of monocytes on pathogen burden, we injected non-activated or IFNγ/LPS-activated bone marrow monocytes into the site of infection during the persistence phase 10 wpi of high-dose infected mice." (PMID 34687607, 2021). "The development of specific T helper 1 (Th1) response, based on the production of proinflammatory cytokines, such as interferon-gamma (IFN-γ), interleukin 12 (IL-12), and tumor necrosis factor-alpha (TNF-α), can protect mammalian hosts from infection by the parasites." (PMID 33928168, 2021). "Humans possess one truncated IRG that likely lacks GTPase activity and only one nontruncated IRG that is not IFNγ or infection inducible." (PMID 34871166, 2021). "The PLS showed that the levels of GMCSF, Fractalkine, IFNg, ITAC, IL-1ß, IL-2, IL-5, IL-7, IL-8, IL-10, IL-12, IL-17α, IL-21, IL-23, MIP-1ß, and TNFα had higher impact on the separation between the uninfected and the pre-infection cohort." (PMID 33731158, 2021).
infection (continued). "Together, our data shows that infection with M. avium strain 25291 induces IFNγ production that alters BM T cell precursors but that other alterations, independent of IFNγ and iNOS, are also required." (PMID 34987496, 2021). "Since we observed, in the acute phase of the infection, significant BMP2, and IFNγ increases, we asked if IFNγ production could be correlated with the BMP2 increase." (PMID 33561140, 2021). "In our study, we found a strong negative correlation between the intestinal IFNγ levels and the number of neurons in the myenteric plexus, especially in the acute phase of experimental infection." (PMID 33561140, 2021). "Using the same approach, we determined the avidities of functional IFNγ+CD8+ T cells specific for non-IDE m18 in the time course in the absence or presence of IDEs after intraplantar infection with mCMVs ΔIDE and rev-IDE, respectively." (PMID 34451420, 2021). "By contrast, localized infection with intranasal instillation of influenza virus and the attenuated Yersinia pestis strain resulted in NK cells producing IFNγ but not IL-10." (PMID 35053151, 2021). "Thus, many immune related proteins are elevated at infection in both cases, such as chemokine ligand 10 (CXCL10), interferon gamma (IFNG), interferon lambda 1 (IFNL1) and chemokine ligand 8 (CCL8)." (PMID 34844191, 2021). "In the absence of IL-4 we found that the levels of IFNγ in pup lungs were not different than in the lungs of P. murina-infected C57BL/6 wild type pups after day 21 post-infection." (PMID 34682248, 2021). "The same phenotypes were observed with RARRES3 ectopic expression irrespective of the presence of STAT1, suggesting that decreased infection on overexpression of RARRES3 is not due to induction of IFNγ signaling." (PMID 34871166, 2021). "This indicated that the absence of the spleen, and corresponding drop in serum IFNγ, results in higher levels of pro-inflammatory signalling in the kidney at 4 h post infection." (PMID 34015044, 2021). "Taken together, our results suggest that early viral control upon infection with SARS-CoV MA15 correlates with a pre-infection increased frequency of circulating T cells with a potential to express IFNg or IL17 rather than TNFa." (PMID 33513210, 2021). "Infection led to increases in proinflammatory CCL2, IFNγ, IL6 and CXCL10 in wt mice." (PMID 34237114, 2021). "In the absence of IFNγ or IL-23p19 the numbers of activated CD62LloCD44hi CD4+ cells in the alveolar spaces were elevated over the wildtype mice at day 31 post-infection." (PMID 34682248, 2021). "Assessment of thoracic (lung draining) lymph node T cell responses during schistosomula lung migration revealed a significant increase in Th2 cell IL-4 expression, but not Th1 cell IFNγ, at days 14 and 21 post 70 cercariae infection." (PMID 33953712, 2021). "Unlike in the migratory ILCs, we do not detect an increase in the MFI for IFNγ in MLNs after STM infection unless we pre-gate on IFNγ+ ILCs." (PMID 33414524, 2021). "We observed that statin treatment decreased IFNγ production and CD107a expression by Vγ9Vδ2 T cells exposed to Lm-infected Mo-DC, suggesting a potential role for endogenous IPP production in Vγ9Vδ2 T cell activation following direct infection." (PMID 34381163, 2021). "The flow cytometry results further supported the absence of specific IFNγ production following PBMC infection with SPPV." (PMID 34211465, 2021). "Mice from CC-RIX lines that had a low lung viral titer at day 2 post-infection had an increased frequency and number of baseline splenic CD8 T cells that could express IFNg as well as IL-17." (PMID 33513210, 2021). "Interestingly, IFNγ, a major inducer of CXCL10, was upregulated following infection of Calu-3 cells, but was still at relatively low levels." (PMID 34205098, 2021). "Thus, the initial control of infection requires the production of IL12, TNFα, and IFNγ by phagocytic cells." (PMID 34946140, 2021).